ENSG00000277941
Gene: Miscellaneous RNA gene on chromosome 22 (26,671,402 to 26,671,550, forward strand). Ensembl gene ENSG00000277941.
Gene Ontology:
Biological process: cell fate specification
Cellular component: nucleus